S100A8 (S100 calcium binding protein A8)
Diseases named in the same sentence as S100A8 in open-access papers (continued):
Sharing a sentence is not in itself a finding about the gene and the disease.
periodontal disease (7 papers, 2013 to 2024). "Correlation with clinical parameters: Biomarkers such as IL-1β, MMP-8, and S100A8 are extensively researched in periodontal disease." (PMID 38192959, 2023). "A recent Korea study reported that salivary S100A8 levels were higher by 70% in periodontal disease than that of healthy participants." (PMID 34372836, 2021). "The proteins S100A8 and S100A9, which are produced by neutrophils and macrophages, can be found in plasma, but their levels in GCF may differ significantly during periodontal disease owing to the local inflammatory response and recruitment of those white cells." (PMID 24098404, 2013).
pterygium (7 papers, 2009 to 2023). A wedge-shaped fibrovascular lesion arising from the bulbar conjunctiva and extending to the cornea. "Pterygium pathogenesis is associated with increased UV exposure and S100A8 protein is known to be induced by UV radiation." (PMID 24825356, 2014). "Compared with the healthy control conjunctiva, the expression of five hub genes (IL1R1, ICAM1, IRAK1, S100A9, and S100A8) in pterygium or pSS samples was statistically significant (p < 0.05)." (PMID 36768371, 2023). "We identified a shared gene signature (IL1R1, ICAM1, IRAK1, S100A9, and S100A8) between pterygium presence and pSS." (PMID 36768371, 2023). "Protein and gene level testing confirmed that the expression level of S100A8/9 proteins in pterygium tissue was higher than that in normal conjunctiva tissue." (PMID 36768371, 2023). "On stimulating cells with S100A8/9, a repertoire of key genes found to be up-regulated in pterygium tissue, were induced in these cells." (PMID 24825356, 2014). "The highly expressed S100A8/9 protein can bind to the keratin filament expressed during terminal differentiation, which may promote the reorganization of cytoskeleton in the process of pterygium hyperproliferation." (PMID 36768371, 2023). "S100A8/9 may be an upstream trigger for inflammation and other disease pathways in pterygium." (PMID 24825356, 2014). "Since these proteins are expressed during terminal differentiation and are associated with intermediate filaments, a functional role in the reorganization of the cytoskeleton during hyperproliferative ocular surface disease such as pterygium may be assumed for S100A8 and S100A9." (PMID 19223989, 2009). "Several DEGs in pterygium and pSS tissues were identified from the datasets, and five hub genes (IL1R1, ICAM1, IRAK1, S100A9, and S100A8) were finally screened out." (PMID 36768371, 2023). "Previously, our group has reported that S100A8 and S100A9 were localized in the superficial layer of both pterygium and normal conjunctiva epithelium, with higher levels in pterygium than uninvolved conjunctiva." (PMID 24825356, 2014). "We further investigated the ability of S100A8, S100A9 and S100A8/A9 to regulate the expression of a panel of genes involved in pterygium pathology using primary cell cultures." (PMID 24825356, 2014). "In pterygium tissue, S100A6 expression increased 2.30 fold, S100A8 increased 3.36 fold, and S100A9 increased 4.01 fold relative to normal conjunctiva." (PMID 19223989, 2009). "Immunofluorescent staining detected the presence of S100A4, S100A6, S100A8, S100A9, and S100A11 in normal human conjunctival and pterygium epithelia." (PMID 19223989, 2009). "Western blot and RT–PCR confirmed the presence of S100A4, S100A6, S100A8, S100A9, and S100A11 in pterygium and conjunctiva tissue." (PMID 19223989, 2009). "S100A4, S100A6, S100A8, S100A9, and S100A11 gene transcripts were detected in conjunctiva and pterygium tissues." (PMID 19223989, 2009). "A similar staining pattern was also observed with the expression of S100A8 and S100A9 in the uninvolved conjunctiva and pterygium." (PMID 19223989, 2009). "Our findings, which showed an increased expression of S100A8 and S100A9 in the superficial layer of pterygium epithelium, support the notion that S100 proteins are centrally involved in cell maturation processes." (PMID 19223989, 2009). "S100A8 and S100A9 were localized in the superficial layer of both pterygium and normal conjunctiva epithelium, with higher levels in pterygium than uninvolved conjunctiva." (PMID 19223989, 2009). "Our investigation revealed that S100A4, S100A6, S100A8, S100A9, and S100A11 are expressed in both the normal and pterygium epithelia." (PMID 19223989, 2009). "In summary, a change in level of expression was detected in S100A6, S100A8, and S100A9 in pterygium tissue relative to the normal conjunctiva." (PMID 19223989, 2009).
pterygium (continued). "Recently, our laboratory detected a marked increase in the expression of S100A8 and S100A9 in the tear fluid of pterygium patients relative to the normal conjunctiva." (PMID 19223989, 2009). "Higher levels of S100A6, S100A8, and S100A9 expressions were detected in the pterygium tissue relative to normal conjunctiva." (PMID 19223989, 2009). "Higher expression levels of S100A6, S100A8, and S100A9 were observed in the pterygium tissue when compared to normal conjunctiva and it has been postulated that these proteins may be associated with the pterygium formation." (PMID 30673862, 2019). "The S100A8 and S100A9 are calcium binding secreted proteins that have been previously identified to be up-regulated in various ocular surface conditions including pterygium, dry eye, meibomian gland dysfunction and corneal neovascularisation." (PMID 24825356, 2014). "The S100A8 and S100A9 have been found to be up-regulated in pterygium tissue." (PMID 24825356, 2014). "However, S100A6, S100A8, and S100A9 transcripts were upregulated (p<0.05) in pterygium relative to normal conjunctiva." (PMID 19223989, 2009). "However, expression of S100A6, S100A8, and S100A9 were markedly greater in the pterygium tissue compared to the uninvolved conjunctival tissue." (PMID 19223989, 2009).
synovitis (7 papers, 2015 to 2025). Inflammation of a synovial membrane. "We clearly demonstrate that the heterodimer S100A8/9 is indeed involved in pain behavior in an experimental model for synovitis." (PMID 32854769, 2020). "Although clearly present in WT and S100A9−/− mice, allodynia was equal between the two groups, excluding a role for S100A8/9 in sensitization in acute synovitis." (PMID 32854769, 2020). "To study the involvement of S100A8/9 in synovitis, we first determined swelling of the knee joint at day 1 and at day 7 after SCW injection." (PMID 32854769, 2020). "Previous studies showed that synovial lining macrophages are crucial in mediating S100A8/A9-driven synovitis during experimental OA." (PMID 31191517, 2019). "This protection is only achieved when ASCs are applied in early CiOA, which is characterized by synovitis and high S100A8/A9 and IL-1β levels, suggesting that inflammation is a prerequisite for the protective effect of ASCs." (PMID 31191517, 2019). "Here, we clearly demonstrate a role for S100A8/9 in pain perception in a model involving synovitis." (PMID 32854769, 2020). "Furthermore, to confirm that CCL3/MIP1α and S100A8 were specific markers of SM, we also immunostained serial sections of synovial tissue from patients with moderate synovitis using the positive control macrophage marker CD68." (PMID 27044395, 2016). "This clear demonstration of lack of pain behavior when S100A8/9 is absent affirms the importance of S100A8/9 in general pain behavior during synovitis." (PMID 32854769, 2020).
abscess (6 papers, 2017 to 2024). An inflammatory process characterized by the accumulation of pus within a newly formed tissue cavity which is the result of a bacterial, fungal, or parasitic infection or the presence of a foreign body. "Furthermore, the influence of S100A8/A9 and the associated immune cells on abscess formation needs further investigations." (PMID 29180834, 2017). "Opposed to this, other groups showed that S100A8/A9 effectively inhibited Staphylococcus aureus outgrowth in locally confined tissue abscesses, due to complexing of essential Mn2+ and Zn2+ ions." (PMID 37467233, 2023). "Due to its release by activated phagocytes at local sites of inflammation, we assumed S100A8/A9 to be a potential biomarker for peritonsillar abscess." (PMID 29180834, 2017). "Particularly, the possibility of the new developed SPTA including S100A8/A9 to identify patients who might profit from medical treatment or whether tonsillectomy or abscess relief is required has to be elucidated." (PMID 29180834, 2017).
anemia (6 papers, 2018 to 2024). A reduction in the number of red blood cells, the amount of hemoglobin, and/or the volume of packed red blood cells. "In particular, high levels of HMGB1 and S100A8/A9 were strongly associated with anemia, which has a multifactorial pathogenesis and remains an unmet medical need in patients with MF." (PMID 39391311, 2024). "With regards to S100A8/A9, patients with higher (upper two quartiles) plasma levels showed higher frequency of anemia, increased blasts (>1%) and inferior survival, HR 5.3 (95%CI 1.7-16.2), P<0.01." (PMID 39391311, 2024).
Cerebral ischemia (6 papers, 2012 to 2025). Restriction of arterial blood supply to the brain associated with insufficient oxygenation to support the metabolic requirements of the tissue. "S100a8 and S100a9, the 11th most upregulated transcript in Trem2−/− mice in our data set, have been shown to play a role focal cerebral ischemia, with a deficiency in both transcripts resulting in diminished disease." (PMID 29040522, 2018). "For patients with brain injury, the S100A8/A9 complex was shown to be involved in the early stage of cerebral ischemia-reperfusion injury." (PMID 32448169, 2020). "S100A8 shows elevated expression in cerebral ischemia and posttraumatic brain injuries." (PMID 23282246, 2012). "Thus it is conceivable, but not proven, that soluble S100A8/A9 contributes to the blood-brain barrier disturbances during cerebral ischemia by stimulating local recruitment of additional leukocytes and induction of cytokine release." (PMID 40656637, 2025). "Interestingly, S100A8 and S100A9 proteins were also detected within our study, confirming that the S100A8/A9 complex has a role in HIE, and has been suggested to be involved in the amplification of neuroinflammation, and cerebral ischemia-reperfusion injury." (PMID 37892154, 2023).
chronic obstructive pulmonary disease (6 papers, 2015 to 2025). A chronic and progressive lung disorder characterized by the loss of elasticity of the bronchial tree and the air sacs, destruction of the air sacs wall, thickening of the bronchial wall, and mucous accumulation in the bronchial tree. "S100A8/A9-induced inflammation via TLR-4 and RAGE activation causes myocardial injury, fibrosis, immune cell infiltration, and electrophysiological alterations, all of which increase the risk of cardiac arrhythmias." (PMID 40948795, 2025). "Together, our data strongly indicate that S100A8/A9 is required for restricting the bacterial burden in the lungs and in the absence of S100A8/A9 there is increased dissemination of bacteria to the heart resulting in severe AV block, cardiac arrhythmia and left ventricular dysfunction." (PMID 37624851, 2023).
Cognitive impairment (6 papers, 2019 to 2024). Abnormal cognition is characterized by deficits in thinking, reasoning, or remembering. "The level of S100A8 is significantly different in different stages of disease and can be used in the diagnosis of cognitive impairment." (PMID 38883967, 2024). "Immunostaining for S100A8 revealed that this population was enriched in the hippocampus, correlating with the cognitive impairment observed in this model." (PMID 38403918, 2024). "For example, TLR4/MyD88 signaling activation by S100A8 promotes neuroinflammation and contributes to tibial fracture surgery-induced cognitive disorders." (PMID 34530841, 2021). "Most importantly, plasma APOE, MMP9, S100A8, UBR5 PLA2G7, and STAT5B play a potentially crucial role in the progression of cognitive disorders." (PMID 38883967, 2024). "Previously, in studies of ex vivo brain tissues in Alzheimer’s and Parkinson’s disease, mild cognitive impairment, and traumatic brain injury, we observed the extra and intracellular amyloid deposits of S100A9, but not S100A8." (PMID 34445262, 2021).
colorectal tumor (6 papers, 2014 to 2024). "In conclusion, our study effectively illustrates the heightened expression of S100A8/S100A9 within colorectal tumor epithelial cells, indicating their crucial role in tumor advancement." (PMID 38817853, 2024). "Mechanistically, The Ca2+-binding protein S100A8 was most obviously downregulated in Sec C-treated colorectal tumor sphere cells, whose relationship with tumor stem cells has not been fully explained before." (PMID 38607060, 2024). "S100 Calcium Binding Protein, S100A9, and S100A8 showed more than a threefold increase in expression in over 80% of colorectal tumor tissue samples in our study." (PMID 38979413, 2024). "Given that overexpressed S100A8 reversed the effect of Sec C on colorectal tumor cells, we continued to test the influence of downregulated S100A8 in the Sec C inhibitory procedure." (PMID 38607060, 2024). "Divalent peptide3A5 suppressed S100A8-mediated interleukin-8 and vascular endothelial growth factor production in human colorectal tumor SW480 cells." (PMID 36932197, 2023). "Next, we wanted to explore whether S100A8 played an important role in the Sec C killing process of colorectal tumor cells." (PMID 38607060, 2024). "We found that S100A8 was highly expressed in those specific cells, implying that S100A8 might have a close relationship with stemness features in colorectal tumor cells." (PMID 38607060, 2024). "Moreover, we observed that Smad4-negative pancreatic and colorectal tumours contain fewer stromal S100A8-positive monocytes than their Smad4-positive counterparts, suggesting a regulated relationship between cancer cells and surrounding monocytic cells." (PMID 30558665, 2018). "Previously, we reported the presence of both S100A8-positive and S100A9-positive stromal monocytes in the tumour microenvironment of pancreatic and colorectal tumours." (PMID 30558665, 2018).
endometriosis (6 papers, 2021 to 2025). The growth of functional endometrial tissue in anatomic sites outside the uterine body. "This study similarly demonstrated that the protein S100-A8 is markedly reduced in the cervical mucus of women with endometriosis." (PMID 39061077, 2024). "S100A8 has been shown to be significantly more abundant in the peritoneal fluid of women with deep endometriosis (stage III-IV of the rASRM classification) during the early stage of the disease (I-II)." (PMID 35204508, 2022). "The pro-inflammatory calcium binding protein S100A8 has already been studied in patients with endometriosis, in samples of peritoneal fluid and cervical mucus." (PMID 34686725, 2021). "A previous study has also reported higher protein levels for S100A8 in peritoneal fluid from patients with deep endometriosis, as compared to patients with superficial lesions." (PMID 34686725, 2021). "Next, lesion tissue sections were stained with S100A8 to determine whether neutrophils recruited to the peritoneum had infiltrated into the developing endometriosis lesions." (PMID 39836475, 2025). "Additionally, another study showed that S100A8 is predominant in the peritoneal fluid of women with early-stage deep endometriosis." (PMID 39061077, 2024). "According to our review of the literature here, COMP, AGT, TGFBI and ANGP4 have not yet been associated with endometriosis, while S100A8, C163A, EGFR and TIMP1 have." (PMID 34686725, 2021). "As S100A8 is known to be involved in inflammatory processes, it is probably not specific to endometriosis, and subsequently, its diagnostic value will be limited." (PMID 34686725, 2021). "In addition, the presence of higher levels of S100A8 in the peritoneal fluid of women with endometriosis suggests its potential contribution to the development and formation of lesions within the peritoneal cavity through inflammatory pathways by activating neutrophils." (PMID 39061077, 2024). "Several members of the S100 protein family were under-expressed in the eutopic endometrium of women with endometriosis during the mid-secretory phase: S100A7, S100A8, S100A9, and S100A12." (PMID 35204508, 2022). "In addition, the protein species 1- antitrypsin, S100-A8, transferrin, and -1b-glycoprotein had significantly higher abundance in patients with ASRM stage III–IV endometriosis than in patients with ASRM stage I– II disease." (PMID 38275362, 2023). "Moreover, cyto-hub gene analysis revealed that CSNK2A1, CSNK2A2, TOP1, PRKACA, RBM39 (plasma), ALB, ACTB, GAPDH, FN1, APOA1 (serum), S100-A9, CXCL1, IL1RN, CSTA, S100-A8 (menstrual blood) and THBS1, ALB, CD44, ANXA2, and LUM (urine) were the top 5 proteins expressed in women with endometriosis." (PMID 39061077, 2024). "There is no literature on S100A8 in the peripheral blood of patients with endometriosis." (PMID 34686725, 2021).
esophageal squamous cell carcinoma (6 papers, 2009 to 2024). Esophageal squamous cell carcinoma (ESCC) is a type of esophageal carcinoma (EC) that can affect any part of the esophagus, but is usually located in the upper or middle third. "The addition of recombinant human S100A8/A9 protein promotes esophageal squamous cell carcinoma cell migration and invasion via the Akt and p38 MAPK signaling pathways, whereas S100A8/A9 silencing suppresses carcinoma cell migration and invasion, as well as Akt and p38 MAPK activation." (PMID 37701037, 2023). "However, decreased expression of S100A8 and S100A9 in Chinese esophageal squamous cell carcinoma were also reported." (PMID 34934042, 2021). "S100A8/S100A9 expression could be detected in 74.4% of lung SCCs, 100% of esophageal SCCs, 100% of cervical SCCs, 96% of oral SCCs, and 95% of skin SCCs stained positive for both S100A8/S100A9." (PMID 31208368, 2019). "For example, almost all members of the S100 family were highly expressed in ESCA, consistent with previous studies demonstrating high expression of S100A7, S100A8, and S100A9 in esophageal squamous cell carcinoma (ESCC), which predicted cancer cell migration and worse overall survival." (PMID 38684596, 2024).
fibrosis (6 papers, 2015 to 2025). the formation of excess fibrous connective tissue in an organ or tissue in a reparative or reactive process. "The “damage-associated molecular patterns” (DAMPs), proteins S100A8/A9 contribute to cardiac fibrosis by activating pro-inflammatory NF-κB signaling in cardiac fibroblasts via the receptor for advanced glycation end products (RAGE) and inducing the expression of multiple chemokines and cytokines." (PMID 29556499, 2018). "It is also referred to as S100A8/A9, MRP8/MRP14 (myeloid-related-protein 8/14), calgranulin A/B, L1 protein, and cystic fibrosis antigen and is composed by two subunits of 8 kDa and 14 kDa, respectively." (PMID 34768386, 2021). "S100A8 and S100A9 are also up‐regulated in K5‐R1/R24, 8 and to a similar extent in K5‐R1/R2/R3 mice, and these cytokines likely contribute to the dermal fibrosis." (PMID 31830366, 2020). "The expression of S100A8, S100A9, S100A8/A9, CCL20, and IL-17, detected by ELISA, is significantly increased in NASH patients with fibrosis in comparison with controls." (PMID 26273651, 2015).